LEP (leptin)
Diseases named in the same sentence as LEP in open-access papers (continued):
Sharing a sentence is not in itself a finding about the gene and the disease.
breast cancer (continued). "Based on the fact that targeting of leptin could be considered as a novel strategy for breast cancer therapy, the aim of this study is the investigation of potentiality of curcumin for inhibition of leptin gene expression and secretion, and also, its link with expression of estrogen receptors." (PMID 25866478, 2014). "Therefore, the inhibition of leptin signaling may be relevant for breast cancer prevention, particularly for obese individuals showing high levels of leptin and occurrence of breast cancer." (PMID 24959279, 2014). "Consequently, SK1 activation is critical for leptin-induced breast cancer cell proliferation." (PMID 25482303, 2014). "Thus, n-3 PUFA antagonism of lipid raft size and composition in BC, as already discussed herein, may also antagonize leptin-mediated proliferative signaling within the mammary tumor microenvironment." (PMID 25360510, 2014). "While this effect is clearly multifactorial and may be linked to changes in sex hormone levels, insulin, adipokines and inflammatory response, leptin reduction may play a role in the achieved outcome and our data show a new mechanism of leptin-mediated effect on breast cancer signalling." (PMID 25482303, 2014). "Given all the potential roles of leptin in the multistep processes of breast cancer progression, involving tumor initiation, primary tumor growth, invasion and metastasis, the leptin-signaling network is emerging as a novel therapeutic target for patients with breast cancers." (PMID 25505738, 2014). "Indeed, leptin levels were increased under hypoxia in trophoblasts and breast cancer via HIF-1α." (PMID 24202338, 2013). "The results from groups A, B and C indicated that elevated leptin levels may promote breast cancer." (PMID 23826274, 2013). "Blocking cancer-stromal cell communication may well be a strategy to target breast cancer therapy, and, interestingly, it has been shown that leptin drives tumour progression by a bidirectional crosstalk between breast cancer cells and cancer-associated fibroblasts." (PMID 24073332, 2013). "For example, leptin, an adipocytokine, is produced mainly by adipose tissue and is known to act as a cancer growth factor, as well as promoting angiogenesis and potentially stimulating the growth of breast cancer cells, thus possibly leading to reduced patient survival." (PMID 22510365, 2012). "Furthermore, estrogens upregulate leptin expression, leading to progression of breast cancer cells." (PMID 23050155, 2012). "Moreover, leptin is a potent inducer of IL-1 system in breast cancer cells." (PMID 21731759, 2011). "However, it is unknown whether leptin regulates IL-1, and whether these effects are related to leptin-induction of VEGF/VEGFR2 in breast cancer." (PMID 21139583, 2011). "Therefore, metformin-based treatments aimed at activating AMPK and restoring the leptin/adiponectin axis may decrease the occurrence of breast cancer in obese patients." (PMID 22203527, 2011). "Moreover, leptin-induced IL-1 could be related to leptin upregulation of essential pro-angiogenic factors in breast cancer: VEGF/VEGFR2." (PMID 21139583, 2011). "Currently, how leptin activates SP1 in breast cancer cells is unknown." (PMID 21139583, 2011). "Leptin upregulation of IL-1 system could further enhance leptin's actions in breast cancer." (PMID 21139583, 2011). "Therefore, it is anticipated that higher concentrations of leptin as those found in serum from obese individuals could impact on the expression of IL-1 in breast cancer." (PMID 21139583, 2011). "Moreover, leptin and IL-1 could have synergistic functions in breast cancer progression promoting VEGF/VEGFR2 expression and tumour macrophage recruitment that could indirectly augment leptin-mediated angiogenic effects and breast cancer growth." (PMID 21139583, 2011).
breast cancer (continued). "Indeed, the hypothesis that leptin is mechanistically related to the development of breast cancer is supported by several breast cancer cell models showing that leptin induces proliferation, survival and anchorage-independent growth." (PMID 19223908, 2009). "Although, in view of some inconsistent reports, the impact of circulating leptin needs further evaluation, one recent study correlated coexistence of high systemic leptin concentrations and high intratumoral ObR mRNA levels with poor prognosis in breast cancer patients." (PMID 18945363, 2008). "Thus, transactivation of HER2 by liganded ObR or by HER1 might constitute an important mechanism of HER2 resistance in breast cancer patients, especially those expressing high levels of leptin and ObR in breast cancer tissues." (PMID 18945363, 2008). "Leptin promotes angiogenesis and might thereby directly stimulate growth of breast cancer cells." (PMID 17010200, 2006). "Lack of oncogene-induced mammary tumors in genetically obese mice, leptin-deficient (ob/ob) mice or leptin-receptor-deficient (db/db) mice have also been discussed in light of this hypothesis." (PMID 17010200, 2006). "A role for leptin in breast cancer tumorigenesis has been hypothesized based on the detection of leptin protein in human breast tumors, the detection of leptin receptors and the proliferative effect of leptin in breast cancer cell lines." (PMID 17010200, 2006). "This study aimed to clarify the mechanisms by which leptin and MTA1 interact to drive VM in breast cancer cells." (PMID 40565190, 2025). "The results showed that leptin, leptin/BMI ratio, FLI and visfatin were significantly higher and soluble leptin receptor ObRe was significantly lower in patients with breast cancer." (PMID 40902078, 2025). "Leptin activates Wnt1 signaling by upregulating MTA1 expression, which induces EMT in breast cancer cells." (PMID 40565190, 2025). "Consequently, leptin is hypothesized to promote VM in breast cancer cells by interacting with MTA1." (PMID 40565190, 2025). "Beyond its classical role, leptin promotes cancer progression including angiogenesis and metastasis; by activating oncogenic pathways, such as the JAK2/STAT3 axis; in breast cancer." (PMID 41463012, 2025). "This study aimed to clarify the mechanism by which leptin and MTA1 interact to induce VM in breast cancer cells, thereby providing new insights into the roles of leptin and MTA1 in tumor progression." (PMID 40565190, 2025). "In this study, we investigated the effects of leptin within extracellular vesicles (EVs) secreted by obese adipose tissue on the functional properties and metabolism of MDA-MB-231 breast cancer cells, a model for triple-negative breast cancer (TNBC)." (PMID 40485730, 2025). "Leptin-activated STAT3 signaling is well known to promote the growth and progression of breast cancer." (PMID 41463012, 2025). "Leptin has been found to upregulate telomerase activity as well as mRNA and protein levels of TERT in human breast cancer cells." (PMID 39692821, 2024). "Separately, leptin-induced NFκB activation also leads to increased expression of IL-1, which in turn promotes VEGF production in breast cancer in vitro." (PMID 39439572, 2024). "In the present study, we exposed breast cancer cells to the ELIT cocktail (17β-estradiol, leptin, IL6, and TNFα) simulating the hormonal and inflammatory conditions of postmenopausal obesity." (PMID 39767718, 2024). "In summary, acupuncture treatment can reduce mitochondrial functional impairment by inhibiting the Leptin/AMPK signaling pathway, thereby improving breast cancer patients." (PMID 37542585, 2023). "VEGF is stimulated by HIF-1α and NFκB and leptin, through the activation of HIF-1α and NF-kB via canonic (MAPK, PI-3K) and non-canonical (JNK, p38 MAP, PKC) signaling pathways, upregulates VEGF in breast cancer." (PMID 37686525, 2023).
breast cancer (continued). "Apart from its endocrine activities, leptin also exhibits various pre-oncogenic mitogenic actions through the LEPR receptor, which is widely expressed in breast cancer cells." (PMID 36900364, 2023). "A novel signal crosstalk between leptin, Notch, and IL-1 (Notch, IL-1, and leptin crosstalk, NILCO) has been demonstrated to drive leptin-induced oncogenic effects in breast cancer." (PMID 38152619, 2023). "Therefore, reducing leptin levels through weight loss, with or without exercise, may help to reduce the risk of recurrence and improve outcomes for breast cancer survivors." (PMID 37571390, 2023). "ObR has been found in breast cancer MCF-7, MDA-MB-231, and HCC 1937 cells, and leptin supplementation stimulated cell proliferation." (PMID 36794014, 2023). "Some cytokines (leptin, IL-1β, IL-6, IL-8, IL-23, IL-17, TGF-β, IL-10) are mostly reported to stimulate while others (Il-2, IL-12, IFNs) inhibit breast cancer proliferation and/or invasion." (PMID 36835413, 2023). "Inversely, serum leptin was shown to be decreased in cats with FMC, which is a trend that has also been noted in pre-menopausal breast cancer patients." (PMID 37626804, 2023). "Support for breast cancer invasiveness and CSC behavior by leptin is mediated through the binding of TGFB1 to its receptor." (PMID 37686525, 2023). "Both LEP and LEPR showed high expression in breast cancer tissues and low expression in benign breast tissues." (PMID 36941557, 2023). "In conclusion, acupuncture treatment can reduce mitochondrial functional impairment by inhibiting the Leptin/AMPK signaling pathway, thereby improving post-chemotherapy fatigue in breast cancer patients." (PMID 37542585, 2023). "It was also reported that leptin enhances the overexpression of HER2 receptor and cell proliferation of HER2+ breast cancer cell lines, which results in resistance to tamoxifen." (PMID 37173907, 2023). "Given that mammary adipocytes are an important component of the tumor microenvironment in mammary cancers, and since leptin is considered to promote breast cancer, our results suggest the possible utility of targeting mammary ME1 for breast cancer treatment." (PMID 37047583, 2023). "Leptin was also reported to activate the STAT3, AKT, and JNK pathways in breast cancer and ovarian cancer." (PMID 37488474, 2023). "The synergistic action between leptin and IL-1 can increase VEGF expression, an angiogenic molecule, in breast cancer." (PMID 38152619, 2023). "The co-culture of ER+ breast cancer cells with obese ASCs activated many pathways such as leptin, IL6, Notch, and jagged canonical Notch ligand 2 (JAG2), which mediated radiation resistance in ER+ breast cancer cells." (PMID 36010901, 2022). "Leptin (LEP) plays a physiological role through its specific receptor (LEPR) and is involved in the occurrence and development of breast cancer." (PMID 35223490, 2022). "In the xenografts model, indeed, it has been shown that the levels of serum estradiol double after 13 days of LEP exposure, whereas in MCF-7 breast cancer cell lines, estradiol administration has enhanced LEP and OB-Rb expression." (PMID 36291602, 2022). "Previous studies indicated that leptin signaling played a key role in breast cancer incidence and development, and a higher expression of leptin and LEPR was also validated in breast cancer tissues." (PMID 35223490, 2022). "The results indicated that except for TFF1 (AUC = 0.774), COL10A1 (AUC = 1.000), LEP (AUC = 0.984), PLIN1 (AUC = 0.966), PGM5-AS1 (AUC = 0.969), and TRHDE-AD1 (AUC = 1.000) were capable of discriminating luminal A breast cancer and normal controls." (PMID 35692369, 2022). "The protein expression results of TUBB3, MCM2, MYOC, FN1, S100A7, and TFF1 were consistent with the mRNA expression result COL10A1, LEP, PLIN1, PGM5-AS1, and TRHDE-AD1 were capable of discriminating luminal A breast cancer and normal controls." (PMID 35692369, 2022).
breast cancer (continued). "Leptin activates the Hedgehog developmental complex, and EMT in breast cancer cell lines (MCF-7, SK-BR-3)." (PMID 36038791, 2022). "ASCs/MSCs secrete various growth factors including IGF1 and EGF, and numerous cytokines such as leptin, IL6, adipsin, and TNFα, which stimulate proliferation and survival of breast cancer cells." (PMID 36010901, 2022). "Honokiol is a potential leptin antagonist, which induces SIRT1/3-mediated activation of LKB1-miR-34a signaling to antagonize tumorigenesis induced by leptin in breast cancer." (PMID 35896782, 2022). "AMPK (involved LIPE and LEP) and PPAR (involved PLIN1) were two significantly enriched pathways in luminal A breast cancer." (PMID 35692369, 2022). "COL10A1, LEP, PLIN1, PGM5-AS1, and TRHDE-AD1 were capable of discriminating luminal A breast cancer and normal controls." (PMID 35692369, 2022). "In human breast cancer cell lines MCF7, MDA-MB-231 and BT-474, the number and expression of SAM68 protein was increased under leptin or insulin stimulation, and insulin and leptin can stimulate SAM68 tyrosine phosphorylation." (PMID 36059653, 2022). "A longer nighttime fast is associated with improved glycemic control, decreased breast cancer biomarkers such as leptin and insulin-like growth factor 1 (IGF-1), and overall reduced breast cancer recurrence." (PMID 35186923, 2022). "For example, adipokines such as LEP and RETN promote metastasis through activation of ezrin, radixin and moesin proteins in breast cancer cells." (PMID 36362348, 2022). "Adipokines overexpressed in TNBC include leptin, resistin, NSMPT, LCN2, and apelin, whereas adiponectin and chemerin are significantly downregulated and their protective role against breast cancer has been suggested." (PMID 36077676, 2022). "Leptin-induced IL-18 expression was regulated via NF-κB/NF-κB1 signaling in TAMs and via PI3K-AKT/ATF-2 signaling in breast cancer cells, which eventually leads to invasion and metastasis in the latter." (PMID 34912237, 2021). "In line with our previously published data in a subset of patients with HR+ breast cancer (n = 24), metabolic evaluations performed in the whole patient cohort showed a significant reduction of circulating levels of c-peptide, IGF1 and leptin after the FMD." (PMID 34439167, 2021). "Herein, taking into account that leptin induces SREBP‐1 in MCF‐7 breast cancer, we have identified SREBP‐1 target genes in response to leptin stimulation, including FASN, ACLY, and FADS2." (PMID 33226729, 2021). "A more specific study on the gene expression of biomarkers in breast cancer revealed that the expression levels of IL-6, TNF-α, and leptin were higher in the breast adipose tissues of women with high waist circumference." (PMID 35008370, 2021). "Leptin also promoted cancer growth and progression by STAT3-mediated upregulation of MMP-13, HER2 and hsp90 in pancreatic and breast cancer cells respectively." (PMID 34588926, 2021). "We measured adiponectin and leptin with ELLA and ELISA on baseline serum samples of 116 Italian postmenopausal women enrolled in two international breast cancer prevention trials." (PMID 34209441, 2021). "In this model, mammary adipocyte-derived leptin not only promotes fatty acid uptake from adjacent adipocytes, but also induces FAO to facilitate the self-renewal and chemoresistance of breast cancer stem cells." (PMID 33535537, 2021). "Leptin is reported to enhance such exosomal cell communication in estrogen positive MCF-7 and triple negative MDA-MB-231 breast cancer cells via hsp90 mediated post-transcriptional increase in the levels of tumor susceptibility gene 101 (Tsg 101) protein." (PMID 34588926, 2021). "A recent study reported that leptin elevates oxygen consumption rate (OCR) and increases the dependence on mitochondrial OXPHOS for ATP production in breast cancer cells." (PMID 33535537, 2021).
breast cancer (continued). "In the present study, we have shown that leptin increases ATP generation by inducing a profound reprogramming in fatty acid metabolism, including FAO and FAS, in estrogen receptor ER‐positive breast cancer cells." (PMID 33226729, 2021). "Suppression of autophagic flux using pharmacological inhibitors or transfection of siRNA targeting LC3B impeded FAO induction by leptin in both MCF‐7 and T47D breast cancer cells, which are essentially similar to the effect on ATP production." (PMID 33226729, 2021). "It has been studied that in breast cancer, PI3K/AKT controls the leptin-mediated-epithelial mesenchymal transition." (PMID 33935708, 2021). "In this study, the role of autophagy in leptin-induced proliferation, migration, apoptosis and ERK phosphorylation in breast cancer cell lines was evaluated." (PMID 33763424, 2021). "Pretreatment with 3‐MA and Bafilomycin A1, which are pharmacological inhibitors of autophagy, significantly suppressed leptin‐induced ATP production in both MCF‐7 and T47D breast cancer cells." (PMID 33226729, 2021). "Recent research established that there is interaction between leptin and adiponectin signaling pathways in MCF-7 breast cancer cell lines, in which proliferation is induced by leptin and suppressed by adiponectin." (PMID 33482868, 2021). "Some in vitro experiments have shown that leptin can increase the expression of cox-2 and members of the PI3K/Akt pathway in cocultures of leptin and breast cancer cells, such as MCF-7, MDA-MB-231 and BT474, to promote tumor growth." (PMID 33842335, 2021). "Leptin derived from obese adipocytes attenuated Tamoxifen’s® treatment efficacy, whereas MCP-1 protected breast cancer cells from 5-Fluorouracil." (PMID 34812105, 2021). "Leptin increased lipid accumulation in a time‐ and dose‐dependent manner in MCF‐7 breast cancer cells." (PMID 33226729, 2021). "Interestingly, neither ATP levels nor cell growth was affected by leptin in MDA‐MB 231 estrogen receptor (ER) negative breast cancer cells, supporting the hypothesis that ATP production and FAO‐mediated via ER‐dependent mechanisms is required for leptin‐induced growth of breast cancer cell." (PMID 33226729, 2021). "They reported that metformin decreased insulin, glucose, leptin, C-reactive protein (CRP), HOMA-IR, and Ki-67 levels, which attenuated the outcome in breast cancer patients." (PMID 33917520, 2021). "Here, we present data showing the involvement of the leptin-mediated signaling pathway in the development of AI therapy resistance, thereby suggesting how blocking leptin signaling could be further exploited for clinical utility in breast cancer resistant settings, especially for obese patients." (PMID 32260113, 2020). "Leptin was found to stimulate OBR expression via STAT3/G9a/miR-200c signaling cascade, and OBR promoted the formation of breast cancer stem-like cells (CSC)." (PMID 33371368, 2020). "Mechanistically, we revealed that adipocyte-derived leptin activated STAT3 to directly enhance PAI-1 expression, or indirectly affect the PAI-1 level by repressing miR-34a, thereby promoting PAI-1-induced breast cancer metastasis." (PMID 33371368, 2020). "Whereas leptin, an adipokine with a central role in obesity, induced JAK2/STAT3 signalling, leading to the promotion of breast cancer stem cell (CSC) survival and self-renewal." (PMID 32731620, 2020). "There is a significant relationship between leptin mRNA and FGFR1 mRNA in normal breast tissue, primary breast cancer tumor tissue, and breast cancer-adjacent tissue; however, there is a difference in the directionality of the relationship." (PMID 33019728, 2020). "Mammary adipocytes also secrete leptin, activating the JAK/STAT3 signalling pathway in breast cancer cells, resulting in the upregulation of the CPT1B gene and FAO." (PMID 32731620, 2020). "Significant differences in the levels of adiponectin, leptin, and FSH were observed between the non-breast cancer group and the breast cancer groups." (PMID 33086618, 2020).